PCP4 (Purkinje cell protein 4)
Diseases named in the same sentence as PCP4 in open-access papers (continued):
Sharing a sentence is not in itself a finding about the gene and the disease.
omodysplasia (1 paper, 2013). Omodysplasia is a rare skeletal dysplasia characterized by severe limb shortening and facial dysmorphism. "Other upregulated genes included GPC6 (loss of function mutations result in the short stature condition omodysplasia) as well as zinc finger protein of cerebellum 1 (ZIC1) and PCP4 both of which are known to be differentially expressed in tumours." (PMID 24148222, 2013).
prostate adenocarcinoma (1 paper, 2025). "A high frequency of PCP4 gene deletion was observed in different prostate adenocarcinoma studies based on cBioportal database." (PMID 40746562, 2025).
salivary gland tumors (1 paper, 2021). "However, no report has investigated the expression of PCP4/PEP19 in salivary gland tumors or MECs to date." (PMID 35008217, 2021).
skin cancer (1 paper, 2018). "The vast heterogeneity of the sample collection with respect to diverse factors like platforms, origin, parts of the body, etc. positively influenced in the finding of 6 genes that had not previously related to skin cancer: SCGB2A1, CRYBA2, ANXA3, PCP4, SOSTDC1 and MYO15A." (PMID 29750795, 2018).
Uterine leiomyoma (1 paper, 2016). The presence of a leiomyoma of the uterus. "PCP4/PEP19 are highly expressed in uterine leiomyoma as compared to non-neoplastic normal myometrium." (PMID 27384474, 2016).
cancer (15 papers, 2012 to 2024). A tumor composed of atypical neoplastic, often pleomorphic cells that invade other tissues. "Among these PCP4/PEP19 and aromatase double positive cancer tissues (15 cases), aromatase expression was diffusely detected and some portions were positive for PCP4/PEP19." (PMID 30038708, 2018). "Most of the cancer tissues (25/30, 83%) were positive for PCP4/PEP19 expression, which localized in both cytoplasm and nuclei." (PMID 25153723, 2014). "Since the expression of PCP4/PEP19 was up-regulated by E2 stimulation in ER-positive MCF-7 cells, the cancer cell survival effects of E2 stimulation would be partially explained by the E2-induced expression of anti-apoptotic PCP4/PEP19." (PMID 25153723, 2014). "The PCP4/PEP19 is a calmodulin-binding anti-apoptotic peptide in neural cells but its potential role in human cancer has largely been unknown." (PMID 25153723, 2014). "This suggests that PCP4/PEP19 may play a dual role in cancer cells, each mediated through the cytoplasm and the nucleus separately." (PMID 25153723, 2014). "We found also several genes underexpressed in subset of cancer samples like KLK3, FOLH1, SPON2, A2M, and PCP4." (PMID 22811706, 2012). "For immune-related genes, the expression of genes involved in the categories of tight junction such as MYH11, PPP2R2C, and MYL9, cancer development such as TAGLN and CALD1, and acquired immunity such as PCP4 and CXCL13 was upregulated in the LP group when compared with that in the CON group." (PMID 37731924, 2023). "PCP4 participates in the calmodulin-dependent kinase signaling pathway to inhibit cell apoptosis, and CCA may promote cancer cell adhesion, migration, and invasion." (PMID 36979826, 2023). "PCP4/PEP19 was localized in both nuclear and cytoplasmic fractions in cancer tissues." (PMID 25153723, 2014). "However, the role of PCP4 alone in cancer remains an open issue, and the changes of PCP4/PEP19 in LUAD have not yet been explored." (PMID 33968130, 2021). "Thus, the expression of PCP4/PEP19 is expected to have a negative impact on prognosis in malignant tumors." (PMID 35008217, 2021). "Hence, locally supplied estrogens by aromatase gene upregulation in PCP4/PEP19 expressed ER- cancer cell population, like SK-BR-3 cell phenotype, would stimulate ER+ cancer cell population to enhance proliferation, migration and invasion, like MCF-7 cell phenotype." (PMID 30038708, 2018). "We found that these cellular processes were inhibited by PCP4/PEP19 knockdown through a mechanism(s) distinct from Bmi-1 signaling, indicating that PCP4/PEP19 enhances cell motility and prevent apoptosis, and therefore can determine malignant potential of cancer cells." (PMID 27384474, 2016).
tumor (12 papers, 2007 to 2025). "A series of molecular and biochemical experiments were carried out in PCa cell lines to investigate the mechanism underlying PCP4-mediated tumor suppression." (PMID 40746562, 2025). "Functionally, PCP4 overexpression suppressed PCa cell and cell-line-derived xenograft tumor growth, whereas PCP4 knockdown exacerbated proliferation and invasion under androgen-depleted conditions compared to adrogen-repletion conditions." (PMID 40746562, 2025). "Gain- and loss-of-function studies in PCa cell lines and mouse models were performed to characterize the role of PCP4 in tumor progression." (PMID 40746562, 2025). "Another program was exclusively found in one ST-RELA tumor, MUV043, and was associated with connective tissue development and extracellular matrix organization (e.g., DLK1, PCP4, ACPT) (ST-RELA-variable)." (PMID 32663469, 2020). "The expression pattern was highly heterogeneous; some tumor cells were positive for either PCP4/PEP19 or aromatase and some were positive for both." (PMID 30038708, 2018). "Furthermore, PCP4 overexpression in C4-2B xenografts in castrated nude mice resulted in delayed tumor progression." (PMID 40746562, 2025). "Furthermore, we identified eight hub genes (VSNL1, TH, PCP4, IGDCC3, RAD51AP2, MUC2, BUB1, and BUB1B) that promoted tumor progression and were associated with prognosis according to the Kaplan–Meier and ROC curve analyses." (PMID 36979826, 2023). "Thus, estrogen may promote cell survival and tumor growth by increasing expression of the anti-apoptotic PCP4 gene and by suppressing the expression of growth inhibitory receptors PTGER3 and TGF-β R2." (PMID 17407572, 2007).
infection (3 papers, 2021 to 2025). The state of being infected such as from the introduction of a foreign agent such as serum, vaccine, antigenic substance or organism. "MA10 infection induced seven additional down-regulated (Hsp90aa1, Tcf7l2, Gnas, Sparcl1, Ywhag, Cpe, Sparc) and four upregulated DEGs (Ppp1r1b, Penk, Arpp21, Pcp4), whereas Aβ pathology resulted in five down-regulated (Cplx1, Syp, Meg3, Snhg11, Penk) and one upregulated DEG (Psen1)." (PMID 41497643, 2025).
neurodegenerative disease (3 papers, 2023 to 2025). A disorder of the central nervous system characterized by gradual and progressive loss of neural tissue and neurologic function. "We also note a downregulation of Purkinje cell protein 4 (Pcp4), a gene that is decreased in various neurodegenerative diseases and also linked to apoptosis." (PMID 40866328, 2025).
neurological disorders (1 paper, 2022). "These genes include MOBP (an oligodendroctye and white matter marker), PCP4 (associated with L5 and L6) and GFAP (associated with astrocytes and many neurological disorders)." (PMID 35380614, 2022).
psychiatric disorder (1 paper, 2023). A disorder characterized by behavioral and/or psychological abnormalities, often accompanied by physical symptoms. "We identified three male-specific genes (ARSA, IGF1R, and SNX19) and two female-specific genes (LEMD2 and PCP4) in psychiatric disorders." (PMID 37794117, 2023).
PCP4 also shares sentences with these, for which no sentence is quoted: Obesity (3 papers); glioblastoma (2); neuroblastoma (2); Parkinson disease (2); Sepsis (2); adenoma (1); adrenocortical tumours (1); Anxiety (1); Autoimmunity (1); bacterial infections (1); bipolar disorder (1); carcinosarcoma (1); chronic periodontitis (1); diabetes (1); endocrine diseases (1); epileptic seizures (1); gastric cancer (1); gastrointestinal tumors (1); glioma (1); Hepatic steatosis (1); Hyperinsulinemia (1); hyperthymia (1); Insulin resistance (1); lung carcinoma (1); major depressive disorder (1); metabolic disorders (1); polycystic ovary syndrome (1); reproductive system diseases (1); retinopathy (1); skin infection (1).
A further 1 disease shares a sentence with PCP4 in 1 paper.